JUN (Jun proto-oncogene, AP-1 transcription factor subunit)
Diseases named in the same sentence as JUN in open-access papers (continued):
Sharing a sentence is not in itself a finding about the gene and the disease.
breast cancer (continued). "Many studies have declaimed that JUN is a biomarker and regulatory gene in breast cancer." (PMID 35127514, 2021). "An inverse relationship was observed between COP1 and c-JUN in a panel of breast cancer cell lines." (PMID 32365809, 2020). "Notably, JUN expression levels were positively correlated with BCLM-associated gene expression and lung metastases in breast cancer patients." (PMID 29667003, 2019). "Our network analysis also allowed us to identify several specific proteins that EGCG may help regulate in breast cancer, including JUN, FADD, NFKB1, Bcl-2, GNAO1, and MMP14." (PMID 28713815, 2017). "Finally, the gene (FOS) from the breast cancer stage II pattern, physically interacts with JUN, a target gene of Vinblastine Breast cancer drug and with NR3C1, a target gene of Megestrol Breast cancer drug." (PMID 26892392, 2016). "In addition, overexpressed JUN partially rescued the migration of breast cancer cells treated with Ponatinib (P < 0.001), which indicated that c-Jun might be a major mediator of Ponatinib’s inhibitory effect on cancer cell migration." (PMID 29667003, 2019). "Except for known disease proteins of breast cancer that found in the 6 protein complexes, many disease proteins that were associated with many other types of diseases could be found, with examples including E2F4, E2F5, HRAS, JUN, FOS." (PMID 24565064, 2014). "Nobiletin inhibits breast cancer cell migration and invasion by suppressing the IL-6-induced ERK-STAT and JNK-c-JUN pathways." (PMID 40328750, 2025). "Here, the authors report that the NOS inhibitor, L-NMMA, sensitises metaplastic breast cancer to a selective PI3K inhibitor, alpelisib, and taxane chemotherapy via repression of c-JUN mediated epithelial-to-mesenchymal transition." (PMID 39737957, 2024). "For this purpose, we used the Gene expression-based Outcome for Breast Cancer Online (GOBO) dataset that contains data about 1881 breast cancer patients to produce a gene set composed of PTGS2/ESR2/EGFR/JUN/ MMP2 genes’ signature." (PMID 39707884, 2024). "These include PTGS2, EGFR, ESR2, MMP2, JUN, and HSP90AB1, which all revealed the highest mRNA expression level in the basal breast cancer subtype, thus proposing a potential similar engagement of these genes in the pathogenesis of the basal subtype." (PMID 39707884, 2024). "To further dissect the biological contributions of the selected PTGS2/ESR2/EGFR/JUN/and MMP2 genes in breast cancer development, we studied their correlation, as a group, to different breast cancer molecular subtypes and ER / HR status." (PMID 39707884, 2024). "Combining the results of network pharmacology with other bioinformatics databases suggests that myrrh’s active components exert anti-cancer effects by regulating genes involved in breast cancer pathogenesis, particularly PTGS2, EGFR, ESR2, MMP2, and JUN." (PMID 39707884, 2024). "Similar results were obtained when examining the co-expression of PTGS2/ESR2/EGFR/JUN/and MMP2 genes’ signature in breast cancer cell lines representative of different molecular subtypes." (PMID 39707884, 2024). "The current analysis further certifies the decisive engrossment of PTGS2/ESR2/EGFR/JUN/MMP2 genes’ signature and some interactor proteins in promoting breast cancer development." (PMID 39707884, 2024). "MALINC1 was also shown to modulate JUN and FOS gene expression and AP-1 complex activity in the early stages of breast cancer and invasive breast carcinoma." (PMID 37240077, 2023). "Because JUN is a common component of JUN/JUN homodimers and JUN/FOS heterodimers 36, we focused to examine JUN expression in breast cancer stroma." (PMID 36438487, 2022).
breast cancer (continued). "As potential upstream regulators of GOLT1B, JUN and SIN3A have been gained increasing attention in diagnosis and treatment of breast cancer." (PMID 35127514, 2021). "The overall survival data showed that the prognosis of breast cancer patients was poorer when two genes (FOS and FOSB) were highly expressed or when four genes (JUN, GADD45B, NR4A1, and BTG2) showed low expression levels." (PMID 34457116, 2021). "In breast cancer cells, overexpressing ci-miRNA-191, was associated with upregulated levels of TGF-β pathway genes (TGFβ2, SMAD3, BMP4, JUN, FOS, PTGS2, CTGF, and VEGFA), thus promoting breast cancer growth and metastasis." (PMID 32942528, 2020). "Various JUN and FOS members have been found to interact with SMADs, and JUNB triggers activation of a TGFβ-induced SMAD-dependent breast cancer invasion program." (PMID 32350443, 2020). "As the product of oncogene JUN, c-Jun directly binds to the GLS promoter which increases gene expression in breast cancer cells." (PMID 32937954, 2020). "The levels of several TGFβ pathway genes, including TGFβ2, SMAD3, BMP4, JUN, FOS, PTGS2, CTGF, and VEGFA, were found to be higher in miR-191-overexpressing breast cancer cells." (PMID 31590453, 2019). "As JUN and FOS are both proto-oncogenes involved in cell proliferation, we investigated the effect of CAAT on breast cancer cell proliferation." (PMID 28525384, 2017). "In particular, we identified JUN, FADD, NFKB1, Bcl-2, GNAO1, and MMP14 as potential targets of EGCG in breast cancer." (PMID 28713815, 2017). "Many of these genes have known roles in cancer gene networks such as the proto-oncogenes JUN and FOS, RAP1A (RAS-related protein 1A), ITGB5, as well as BRCA2 (Breast cancer 2, early onset) and PCNA (Proliferating cell nuclear antigen)." (PMID 26448646, 2015). "The AP1-complex members c-JUN and c-FOS are involved in the activation of the promoter of MMP1 in MDA-MB-321 breast cancer cells secondary to the activation of ZEB1, a transcription factor involved in EMT." (PMID 24586640, 2014). "Moreover, the GOBO analysis shows an elevated expression profile of the PTGS2/ESR2/EGFR/JUN/MMP2 genes’ signature in the most aggressive breast cancer subtype (Basal) in breast tumor samples and breast cancer cell lines." (PMID 39707884, 2024). "In this study, we used a set of cell lines, including two melanoma cell lines HMCB and CHL1 (where UV is a major carcinogen), HeLa (cervical carcinoma cell line in which JUN expression was intensively studied) and MDA-MB-231 (breast cancer-TNBC; a cancer type in which JUN plays a significant role)." (PMID 38565943, 2024). "JUN overexpression is observed in various cancers, such as non-small-cell lung cancer, breast cancer, and vulvar cancer, but there is no direct evidence linking JUN overexpression with gastrointestinal cancer." (PMID 36834821, 2023). "We found a correlation between the expressions of JUN mRNA and STC1 mRNA in the metastases of breast cancer patients, suggesting that there may be a regulatory relationship between c-Jun and STC1." (PMID 37400459, 2023). "Importantly, MSCs can induce the spread of cancerous cells; Breast cancer cells treated with MSCs showed overexpression of oncogenes (NCOA4, FOS), proto-oncogenes (FYN, JUN), and EMT-specific markers, leading to breast cancer metastasis." (PMID 37849741, 2023). "Moreover, the PPI network uncovered the crucial roles of numerous proteins (e.g., FOXP3, STAT1, STAT4, FOXP3, JUN, and CD3D) in breast cancer." (PMID 36704358, 2022).
breast cancer (continued). "Specifically, we find that activated JUN in stroma is necessary and sufficient to remodel CAF-specific enhancer landscape, promotes the expression of pro-metastatic genes and thereby augments breast cancer invasiveness." (PMID 36438487, 2022). "We examined genes that co-expressed with GLUT1 and JUN in breast cancer in Adorno cell line dataset, and found that the transcription level of GLUT1 and JUN were closely corelated and might contribute to certain signaling pathways." (PMID 36476606, 2022). "Our study proclaimed that the altered phosphorylation of two potential transcription factors of GOLT1B, JUN and SIN3A, might be responsible for the increased GOLT1B expression in breast cancer." (PMID 35127514, 2021). "When breast cancer cells were directly co-cultured with MSCs, they demonstrated substantial overexpression of oncogenes (NCOA4, FOS), proto-oncogenes (FYN, JUN), and EMT specific markers, as well as shape and growth pattern changes, resulting in breast cancer metastasis." (PMID 34736460, 2021). "Finally, we observed that knocking down Vimentin suppressed p-PI3K, p-AKT, c-JUN, c-Myc, and Cyclin D1(CCND1), N-cadherin and restored E-cadherin expression in MAP2K4-overexpressed breast cancer cells." (PMID 31761784, 2019). "Similarly, the top hub TFs we found in the integrated network such as SP1, SP2, TCF12, MYC, JUN and EGR2, were also well-known regulators in breast cancer." (PMID 26763900, 2015). "Overexpression of c-JUN has been shown in several human cancer types such as non-small cell lung cancer, breast cancer, colon cancer and lymphomas." (PMID 24466173, 2014). "“All of the mouse and most human mammary tumors also displayed decreased expression of genes known to inhibit cell proliferation, including NFKBIA (IKBalpha), GADD45B, and CDKN1A (p21); transcription-related genes such as CEBP, JUN, JUNB, and ELF1;....”." (PMID 23216862, 2012). "Additionally, TB activated immune-related pathways via ERK/MAPK signaling and upregulated genes such as SMAD2, SMAD3, and JUN.Conclusions: TB functions as an HSP90 inhibitor with dual anticancer and immunomodulatory properties in Estrogen Receptor-Positive (ER+) breast cancer cells." (PMID 41304910, 2025). "And through gain and loss-of-function studies, we demonstrate that activated JUN is necessary and sufficient to remodel enhancers and maintain the activation of CAF-specific enhancers, and thereby promotes breast cancer invasiveness in a non-cell-autonomous manner." (PMID 36438487, 2022). "Moreover, by enhancing the levels of EGFR, HB-EGF, JUN and, in particular, FOS family members, ΔNp63 can enable sustained activation of the pro-oncogenic gene program induced by SMADs and AP-1 in HER2+ and/or EGFR+ breast cancer cells." (PMID 32350443, 2020). "For instance, the activation of JUN is underscored as a pivotal factor in the activation of cancer-associated fibroblast-specific (CAF-specific) enhancers, promoting the expression of pro-metastatic genes and, thereby, augmenting breast cancer invasiveness in a non-cancer-cell-autonomous manner." (PMID 40032852, 2025). "After a multi-omics analysis, we uncovered that the higher expression of GOLT1B in breast cancer tissues versus normal tissues might be due to the amplification of GOLT1B and altered phosphorylation of its potential transcriptional factors, including JUN and SIN3A." (PMID 35127514, 2021). "Interestingly, in basal-like and mesenchymal breast cancers the PI3K-AKT and MEK-ERK pathways are often activated, resulting in high levels of JUN and FOSL1, whereas luminal A breast cancers do not show activation of the ERK1/2 MAP-kinase pathway." (PMID 32350443, 2020).
melanoma (137 papers, 2010 to 2026). A malignant, usually aggressive tumor composed of atypical, neoplastic melanocytes. "Melanoma cells have a well-defined stressed cell state, which is marked by the upregulation of immediate early transcription factors (JUN, FOS, ATF3, NR4A1, DUSP) linked to melanoma oncogenic programs, inflammation, and stress response." (PMID 36765834, 2023). "Development of c-JUN-mediated mesenchymal-like phenotype: Vemurafenib resistance in BRAFV600E melanoma cell lines is associated with a high abundance of c-JUN and characteristics of a mesenchymal-like phenotype." (PMID 37834284, 2023). "This shift facilitates increased EP300 interaction at JUN-transcriptional sites while reducing its association with melanocyte-inducing transcription factor sites, promoting melanoma cell invasion and resistance to stress, ultimately leading to enhanced metastatic potential." (PMID 40016470, 2025). "JUN upregulation has been associated with melanoma treatment resistance to classical chemotherapy." (PMID 27648299, 2016). "To address the global relevance of c-Jun induction in the context of MITF loss for inflammatory hyperresponsiveness of melanoma cells, we performed co-knockdown experiments with siRNAs against MITF and c-JUN in the absence or presence of TNF-α and analysed the transcriptional changes by microarray." (PMID 26530832, 2015). "Clinically, melanoma patients exhibiting elevated necroptosis-related signatures, such as JUN and HMOX1 expression, show improved responses to ICB therapy and prolonged progression-free survival." (PMID 41235238, 2025). "In myeloid precursor cells, MITF was shown to interact with EOS to recruit co-repressors to target genes, whereas in melanoma cells MITF bound directly to an E-box located in an enhancer of the c-JUN gene, leading to reduced expression of the gene." (PMID 33438577, 2021). "In a different previous study, researchers demonstrated that a high level of JUN was correlated with the inherent resistance to BRAFi/MEKi in melanoma cells." (PMID 32413516, 2020). "We conclude that dysregulation of CDK6 by JUN mediates resistance to BRAF inhibition in melanoma cells." (PMID 32413516, 2020). "Through loss-of-function screens, transcriptomics, and epigenetic profile analysis, we have identified a network that includes CDK6, ETV5, and JUN as the potential mechanism for BRAFi-resistant melanoma cells." (PMID 32413516, 2020). "In BRAF inhibitor-resistant melanoma cells, JUN was characterized as a mediator of upregulated PD-L1 expression." (PMID 27648299, 2016). "In BRAF inhibitor-naive melanoma, JUN has been reported as a regulator of tumor progression and as a potential therapeutic target." (PMID 27648299, 2016). "Western blot analysis revealed decreased amounts of phosphorylated JNK and c-JUN in melanoma cells treated with WZB117." (PMID 26293674, 2015). "In melanomas, it has been demonstrated that c-JUN protein, together with CEBP/ß TF, was involved in transcriptional regulation of a specific melanoma differentiation associated gene (mda-7)." (PMID 24086527, 2013). "One such approach involves the use of the antiarrhythmic drug propafenone, which sensitizes melanoma cells to necroptosis by activating the JNK/JUN signaling pathway, upregulating mitochondrial heme oxygenase 1 (HMOX1), and inducing iron overload and ROS accumulation." (PMID 41235238, 2025). "To explore whether ROS induction mediated by trametinib plus CuET is essential for the upregulation of JUN in BRAF WT melanoma cells, we analyzed JUN expression following treatment with the combination in the presence of the ROS scavenger NAC." (PMID 38263136, 2024). "In addition, while our study focused on the circJUN‐miR‐3064 interaction, other miRNAs such as miR‐125b have been shown to inhibit c‐JUN and suppress melanoma progression." (PMID 39307884, 2024).
melanoma (continued). "To further investigate whether JNK/JUN signaling was activated by the combination therapy, we analyzed melanoma cells for JNK phosphorylation and JUN accumulation following treatment with trametinib and CuET by Western blotting." (PMID 38263136, 2024). "We therefore investigated whether this JNK/JUN signaling axis was involved in the cell death induced by trametinib plus CuET in melanoma cells." (PMID 38263136, 2024). "Overall, these observations suggest that CDK6 up-regulated by TFs JUN and ETV5 might be associated with BRAFi resistance in melanoma patients." (PMID 32413516, 2020). "Additional evidence that CDK6, ETV5, and JUN may confer resistance to BRAF inhibition comes from our analysis of two independent melanoma cohorts." (PMID 32413516, 2020). "Furthermore, the AP-1 family member c-JUN is a key factor involved in melanoma progression, responsible for gene deregulation in MAPK and PI3K pathways." (PMID 32296574, 2020). "MC1568 has been shown to decrease cell proliferation and IL-8 production in human melanoma cells, suppress c-JUN which is a transcriptional target of MEF-2 transcription factors and also suppress the activity of histones 3 and 4, RNA polymerase II and TFIIB to the c-JUN promoter." (PMID 31105874, 2019). "We treated three additional BRAFV600E-positive melanoma cell lines with vemurafenib and found that each and every persistent cell population displayed consistent upregulation of JUN and phospho-JUN upon short-term BRAF inhibitor exposure." (PMID 27648299, 2016). "JUN knockdown by itself only minimally affected untreated parental melanoma cells." (PMID 27648299, 2016). "In addition to its increase in net phosphorylation levels, JUN is transcriptionally upregulated in the resistant and the ‘invasive phenotype’ melanoma cells." (PMID 27648299, 2016). "Several transcription factors, including ZEB1/2, SNAIL1/2, TWIST1/2, MITF and JUN, have been shown to play key roles in melanoma EMP-like processes; however, the mechanisms by which internal and micro-environmental signals are integrated to modulate transcriptional activity are not fully understood." (PMID 27852308, 2016). "In addition, we found that JUN upregulation is a common treatment response in melanoma patient samples." (PMID 27648299, 2016). "SOX10, MITF, and JUN were significantly regulated in melanomas in comparison with cancer." (PMID 26044366, 2015). "Re-analysis of the gene expression data from our TNF-stimulated melanoma cell line panel consistently revealed that suppression of MITF mRNA significantly correlated with the reciprocal induction of c-JUN mRNA, but obviously this switch was variable among the different cell lines." (PMID 26530832, 2015). "Additionally, c-JUN induces an EMT-like phenotype switch that may be responsible for the adaptive resistance to BRAF-MEK-ERK pathway inhibition in BRAFV600E melanoma cells." (PMID 40481178, 2025). "However, an EGR1 -like pattern of gene expression was observed for JUN, indicating that the intensity of expression of the EGR1, FOS, IER2, and JUN transcription factor genes could be coregulated at least in some human melanomas." (PMID 39436655, 2024). "Interestingly, JUN proteins are involved in melanoma migration." (PMID 28761621, 2017). "Pseudotime trajectory analysis identified critical genes (CYR61, JUN, RHOC) involved in melanoma cell state transitions." (PMID 41993933, 2026). "Our multi-omics analysis revealed PRKD1, JUN, and NCK1 as key resistance nodes, offering potential targets for therapeutic strategies to counter resistance in melanoma." (PMID 41708984, 2026). "This demonstrates that activation of the JNK/JUN pathway is crucial for combination therapy-mediated apoptosis induction and cytotoxicity in BRAF WT melanoma cells." (PMID 38263136, 2024). "Module M3 contained JUND, SOX2, THAP11, and JUN, as well as regulators for C5 Melanoma MAGEA4, C6 Melanoma GJB2, C2 melanoma EDNRB, and C1 melanoma CDH19." (PMID 37435067, 2023).